LRP1 (LDL receptor related protein 1)
Diseases named in the same sentence as LRP1 in open-access papers (continued):
Sharing a sentence is not in itself a finding about the gene and the disease.
triple-negative breast carcinoma (3 papers, 2022 to 2024). An invasive breast carcinoma which is negative for expression of estrogen receptor (ER), progesterone receptor (PR), and human epidermal growth factor receptor 2 (HER2). "LRP1 repressed xenografts of triple negative breast cancer cell lines have been shown to decrease tumour growth and angiogenesis." (PMID 39010058, 2024). "We injected wild-type C57BL6/J mice and LysM-Cre-LRP1−/− mice with the murine triple-negative breast cancer cell line E0771, which express similar levels of PRSS2 to Pan02 cells and even greater levels than SUM159 cells." (PMID 36575174, 2022).
Anxiety (2 papers, 2019 to 2023). Intense feelings of nervousness, tension, or panic often arise in response to interpersonal stresses. "The decrease in food intake and body weight and the increase in anxiety induced by VacA might be caused by the interactions between VacA in the PVN via the humoral pathway and hypothalamic LRP1." (PMID 30979915, 2019).
aortic atherosclerosis (2 papers, 2023 to 2024). A atherosclerosis that involves the aorta. "HL also facilitates the uptake of chylomicrons, chylomicron remnants, VLDL-C, and HDL-C via LRP1 into various cell types and protects against aortic atherosclerosis." (PMID 37425327, 2023).
autism (2 papers, 2022 to 2023). Persistent deficits in social interaction and communication and interaction as well as a markedly restricted repertoire of activity and interest as well as repetitive patterns of behavior. "Many of these CNVs encompass genes included in the best‐known lists of candidate genes for autism, including CTNNA3 (OMIM #607667), MACROD2 (OMIM #611567), IMMP2L (OMIM #605977), PARK2 (OMIM #600116), LZTS2 (OMIM #610454), and LRP1 (OMIM #107770)." (PMID 37186221, 2023).
cardiomyopathy (2 papers, 2012 to 2013). A disease of the heart muscle or myocardium proper. "Thus, smooth muscle cell Lrp1 deficiency results in aortic dilation and insufficiency that causes secondary cardiomyopathy that can be improved by captopril." (PMID 24312398, 2013). "This study was undertaken to test the hypothesis that vascular defects due to smooth muscle Lrp1 deficiency directly lead to cardiomyopathy as the animals progress in age, and to determine if the mechanism is primary or secondary to valvular disease." (PMID 24312398, 2013). "This study used echocardiography and blood pressure monitoring in mouse models to determine whether inactivation of Lrp1 in vascular smooth muscle leads to cardiomyopathy, and if so, whether the mechanism is a consequence of valvular disease." (PMID 24312398, 2013). "Therefore, our results suggest that cardiac alterations associated to the deleterious effects of myocardial cholesterol accumulation may be modulated through LRP1 targeting in heart failure and cardiomyopathy." (PMID 22873206, 2012).
cervical cancer (2 papers, 2019 to 2025). A primary or metastatic malignant neoplasm involving the cervix. "In cervical cancer, LRP1 expression was potentially linked to tumor development." (PMID 40777026, 2025). "High LRP1 expression was associated with low differentiation in cervical cancer and a shorter overall survival (OS) in patients, suggesting that LRP1 could serve as an effective prognostic factor for poor clinical outcomes in cervical cancer." (PMID 40777026, 2025). "The expression of LRP1 in cervical cancer tissues was found to differ from that in normal cervical tissue." (PMID 40777026, 2025). "Studies indicated that aberrant LRP1 expression in cervical cancer might contribute to poor therapeutic outcomes." (PMID 40777026, 2025). "However, despite the fact that hemin was able to induce autophagy in non-hematopoietic cell lines such as HeLa (cervical cancer cells), it did not induce any changes in the LRP1 levels." (PMID 30523204, 2019).
congenital heart defects (2 papers, 2020 to 2023). "We previously identified a homozygous missense mutation in this Lrp1 in mice cause congenital heart defects (CHDs), including atrioventricular septal defect (AVSD) and double outlet right ventricle (DORV)." (PMID 37107705, 2023). "A homozygous missense mutation in the LDL receptor-related protein 1 (Lrp1) in mice was shown to cause congenital heart defects, including atrioventricular septal defect (AVSD) and double outlet right ventricle (DORV)." (PMID 37107705, 2023).
cutaneous melanoma (2 papers, 2017 to 2022). A primary melanoma arising from atypical melanocytes in the skin. "The LRP1 expression was lower in the tumor than in adjacent normal human skin melanoma tissues." (PMID 36612285, 2022). "Thus, it could advance the field and provide the basis for further study of the LRP1 inhibitor in cutaneous melanoma." (PMID 29138479, 2017).
demyelinating disease (2 papers, 2020 to 2023). A broad group of disorders that affect the myelin sheaths that cover the neurons. "Upregulation of C3, Nrp2, Lrp1 was observed in demyelinating disease." (PMID 36817487, 2023).
developmental delay (2 papers, 2018 to 2021). "In addition, we identify two potentially novel associations: LRP1 in early-onset drusen formation and UBE2U in a multi-system condition presenting with retinoschisis, cataracts, learning disabilities, and developmental delay." (PMID 33776059, 2021).
dilated cardiomyopathy (2 papers, 2013 to 2020). Cardiomyopathy which is characterized by dilation and contractile dysfunction of the left and right ventricles. "This study demonstrated that cardiovascular deficiency of Lrp1 causes vascular changes resulting in aortic dilation and insufficiency and development of dilated cardiomyopathy." (PMID 24312398, 2013). "Our team has previously shown that LRP1 membrane compartmentalization is altered in human myocardial samples from dilated cardiomyopathy patients." (PMID 31936892, 2020). "Thus, smooth muscle Lrp1 deficiency may potentially cause cardiac dysfunction via several mechanisms, such as aortic root dilation leading to aortic insufficiency and the subsequent development of dilated cardiomyopathy secondary to valve disease." (PMID 24312398, 2013).
fibrosis of the liver (2 papers, 2021 to 2023). "LRP1 can improve liver fibrosis by modulating hepatic stellate cells proliferation and migration." (PMID 33644047, 2021).
heart failure (2 papers, 2012 to 2017). Inability of the heart to pump blood at an adequate rate to meet tissue metabolic requirements. "Three different receptors have to be taken into account: LDL receptors, known to act as LDL transport molecules in the liver, LDL receptor-related protein-1 (LRP-1), known to improve load-free cell shortening in these cells, and LOX-1 that has been associated with heart failure." (PMID 28913715, 2017).
Hydrocephalus (2 papers, 2009 to 2011). Hydrocephalus is an active distension of the ventricular system of the brain resulting from inadequate passage of CSF from its point of production within the cerebral ventricles to its point of absorption into the systemic circulation. "The present study has examined LRP-1, RAGE, Aβ, and GFAP in neonatal animals after intraventricular (obstructive) hydrocephalus was induced by kaolin injections into the cisterna magna at 1 day of age and ventriculomegaly had progressed until 21 days of age." (PMID 19470163, 2009). "Previous studies in aging animals have shown that amyloid-beta protein (Aβ) accumulates and its transporters, low-density lipoprotein receptor-related protein-1 (LRP-1) and the receptor for advanced glycation end products (RAGE) are impaired during hydrocephalus." (PMID 19470163, 2009).
hyperplasia (2 papers, 2022 to 2023). An abnormal increase in the number of cells in an organ or a tissue with consequent enlargement. "Low-density lipoprotein receptor-related protein 1 (LRP1), apolipoprotein E receptor-2 (ApoER2), very-low-density lipoprotein receptor (VLDL-R), and other receptors can promote vascular endothelial hyperplasia and increase lipoprotein concentrations." (PMID 36230934, 2022). "In addition, binding to low-density lipoprotein receptor-related protein 1 (LRP1), apolipoprotein E receptor-2 (ApoER2), very-low-density lipoprotein receptor (VLDLR), and other receptors promotes vascular endothelial hyperplasia and increases lipoprotein levels." (PMID 36980904, 2023).
hypertriglyceridemia (2 papers, 2019 to 2020). A laboratory test result indicating elevated triglyceride concentration in the blood.
idiopathic dilated cardiomyopathy (2 papers, 2017). Decreased function of the heart associated with cardiac enlargement and congestive heart failure, of unknown cause. "LRP is highly expressed in cardiomyocytes and a soluble form of LRP1 is elevated in the serum of idiopathic dilated cardiomyopathy patients." (PMID 28920060, 2017).
injury (2 papers, 2022 to 2025). Damage inflicted on the body as the direct or indirect result of an external force, with or without disruption of structural continuity. "In addition to IL-4 and IL-10, low-density lipoprotein receptor-related protein-1 (LRP1) also enhanced the M2 polarization of microglia after acute brain injury and improved neurological injury." (PMID 36296682, 2022).
Lewy body dementia (2 papers, 2024 to 2025). A progressive form of dementia characterized by the presence of protein deposits called Lewy bodies in the midbrain and cerebral cortex, and loss of cholinergic and dopaminergic neurons. "Additionally, α-synuclein, found in Lewy bodies of both Lewy body dementia and PD, can also be cleared from the brain via LRP1-mediated transcytosis." (PMID 39030617, 2024).
memory impairment (2 papers, 2019 to 2024). "Our study is the first to investigate whether LRP1 level is associated with improved memory impairment using the PPAR-γ agonist, pioglitazone, in the SAMP8 mouse model." (PMID 30867485, 2019). "Chronic antisense inhibition of LRP1 via intracerebroventricular infusion not only reduced Aβ efflux from the brain but it also led to memory impairment in WT mice." (PMID 39065645, 2024). "Our finding suggests a theoretical basis for the use of pioglitazone in treating AD, by demonstrating the efficacy of low-dose pioglitazone in the improvement of memory impairment and Aβ pathology-related LRP1 expression in a mouse model of AD." (PMID 30867485, 2019).
Myocardial fibrosis (2 papers, 2023 to 2025). "These cells interact with EndoCs, ECs, and macrophages through the Cxcl12-Ackr3, Ptn-Ncl, and Mdk-Lrp1 signaling pathways, thereby influencing myocardial fibrosis progression." (PMID 40595870, 2025).
myocardial ischemia (2 papers, 2013 to 2025). A disorder of cardiac function caused by insufficient blood flow to the muscle tissue of the heart. "This study aims to investigate the relationship between LRP1 expression and myocardial ischemia, and to evaluate its potential as a prognostic marker in STEMI patients undergoing PCI." (PMID 40083817, 2025).
pulmonary arterial hypertension (2 papers, 2022 to 2023). Pulmonary arterial hypertension (PAH) is a group of diseases characterized by mean pulmonary artery pressure >20 mmHg and elevated pulmonary arterial resistance leading to right heart failure. "Lrp1 deletion in vascular smooth muscle cells resulted in spontaneous development of pulmonary arterial hypertension by lifting the inhibition of the TGF-β-connective tissue growth factor axis." (PMID 35202607, 2022).
rheumatoid arthritis (2 papers, 2014 to 2016). A chronic, systemic autoimmune disorder characterized by inflammation in the synovial membranes and articular surfaces. "Although monocytes isolated from SLE patients showed only a modest decrease in CD91/LRP1 levels, patients with rheumatoid arthritis or SLE showed significantly elevated levels of soluble CD91/LRP1 cleaved by ADAM17 in response to inflammation." (PMID 25426118, 2014). "Under inflammatory conditions such as in rheumatoid arthritis and systemic lupus erythematosus, MMP-13 transcription is elevated, and LRP1 shedding is also increased." (PMID 27084377, 2016).
synucleinopathies (2 papers, 2022). "Evidence from diseased brains will be needed to further support the role of LRP1 in the etiology of α-synucleinopathies." (PMID 36435812, 2022). "This study provides new knowledge on the physiological and pathological role of LRP1 in α-Syn trafficking and pathology, offering insight for the treatment of synucleinopathies." (PMID 36056345, 2022). "Illustrating the role of LRP1 in the transmission of α-syn, particularly monomers and oligomers, provides critical insights into the interneuronal transmission mechanism of α-syn, and highlights LRP1 as a promising drug target to block the spreading of oligomeric α-syn in α-synucleinopathies." (PMID 36435812, 2022). "This study highlights LRP1 as a promising drug target for α-synucleinopathies." (PMID 36435812, 2022).
systemic lupus erythematosus (2 papers, 2016 to 2017). An autoimmune multi-organ disease typically associated with vasculopathy and autoantibody production. "LRP‐1 shedding is increased under inflammatory conditions such as in RA and systemic lupus erythematosus 28, and in cancer 29, 30, but the exact pathologic role of LRP‐1 shedding in these diseases has not been clearly understood." (PMID 28235248, 2017).
acute kidney injury (1 paper, 2020). Sudden and sustained deterioration of the kidney function characterized by decreased glomerular filtration rate, increased serum creatinine or oliguria. "While Hx directs heme to the liver and mediates its hepatic up-take via the scavenger receptor low-density lipoprotein receptor-related protein-1 (LRP1, synonymous with CD91), A1M directs heme to the kidney where it may cause detrimental effects including acute kidney injury." (PMID 32983129, 2020).
adenoma (1 paper, 2018). A neoplasm arising from the epithelium. "Furthermore, IHC analyses performed on 14 conventional adenomas (8 low-grade, 6 high-grade) revealed that LRP1 IHC score was significantly higher in adenoma cells when compared with adenocarcinoma cells (data not shown), and this whatever the grade." (PMID 29507659, 2018).
allergic rhinitis (1 paper, 2023). Inflammation of the nasal mucous membranes caused by an IgE-mediated response to external allergens. "Similarly, the transcriptional regulation of LRP1 altered by rs1385526 in smooth muscle cells and PGAP3 altered by rs10558975 in enterocytes were considered to underlie hayfever/allergic rhinitis and inflammatory bowel disease (IMD), respectively." (PMID 37391400, 2023).
apical periodontitis (1 paper, 2025). "In turn, several lead SNPs of Necrosis of pulp or apical periodontitis may associate with tumour suppression (LRP1, CAMD2, MCPH1), while others are involved in plasma membrane structure, assembly, and transport." (PMID 40701953, 2025).
astrocytic tumor (1 paper, 2022). A glial tumor of the brain or spinal cord showing astrocytic differentiation. "Further, when we subdivided the cases of the TCGA database based on the IDH status, the wild type GBM cases had a significantly higher LRP-1 expression than the IDH mutated grade 4 astrocytic tumor similar to the index study." (PMID 36267880, 2022). "Two separate studies from the same group of authors qualitatively reported the presence of LRP-1 mRNA in cases of astrocytic tumors by reverse transcriptase PCR." (PMID 36267880, 2022). "Both LRP-1 and ABCA-1 high expression was associated with significantly shorter survival when all the astrocytic tumor cases and GBM were assessed together." (PMID 36267880, 2022). "High protein expression of LRP-1 and ABCA-1 was associated with significantly shorter survival when all the astrocytic tumors, including GBM, LGA, and HGA assessed together (Estimated mean OS for LRP-1 – 70.0 vs. 100.3 weeks; Estimated mean OS for ABCA-1– 62.3 vs. 116.2 weeks)." (PMID 36267880, 2022). "Hence, it is possible that IDH may have important role in the expression of LRP-1 in astrocytic tumors." (PMID 36267880, 2022). "LRP-1 and ABCA-1 mRNA expression and immunohistochemical expression score in GBM (Gr 4), IDH wild type (WT) and comparison with astrocytic tumors (Gr 4), IDH Mut [HGA] and astrocytic tumors (Gr 2/3), IDH Mut [LGA]." (PMID 36267880, 2022). "Similar to LRP-1, the expression of ABCA-1 was also significantly higher in cases of all GBM and other diffusely infiltrating astrocytic tumor as compared to the normal brain." (PMID 36267880, 2022). "In contrast, all cases of astrocytic tumors showed LRP-1 immunopositivity irrespective of tumor grade." (PMID 36267880, 2022). "When we compared the expression of LRP-1 between the IDH mutated low- (grade 2/3) and high-grade (grade 4) astrocytic tumor, the difference was not statistically significant at protein or mRNA level." (PMID 36267880, 2022).
atrioventricular septal defect (1 paper, 2023). "Interestingly, there is a significant relationship between those variants that have an allele frequency below 0.01% and atrioventricular septal defect, which is the phenotype observed previously in a homozygous N-ethyl-N-nitrosourea (ENU)-induced Lrp1 mutant mouse line." (PMID 37107705, 2023).
atrophic gastritis (1 paper, 2023). "Polymorphisms of LRP1 may be associated with CagA accumulation and atrophic gastritis." (PMID 37198664, 2023).
atrophic rhinitis (1 paper, 2022). A chronic inflammation in which the nasal mucosa gradually changes from a functional to a non-functional lining without mucociliary clearance. "In line with the role of LRP1 in PMT pathophysiology of atrophic rhinitis, LRP1 signaling itself has been suggested to be involved in the differentiation of bone marrow derived macrophages into osteoclasts." (PMID 36516199, 2022).
benign ovarian tumors (1 paper, 2021). "Our own results extend these findings and indicate that specific patterns of lipoprotein gene expression (LSR-high/VLDLR-low/LRP1-low) are a distinguishing feature of malignant versus benign ovarian tumors." (PMID 34518593, 2021).
bladder tumors (1 paper, 2023). "By comparing BLCA-related signatures, we found that bladder tumors with high LRP1 expression tend to have basal differentiation, a greater amount of fibroblastic and smooth muscle cells, and a larger immune infiltration." (PMID 37153545, 2023).
bone fracture (1 paper, 2024). "Studies on mouse models of bone fracture showed that the age-related decline in bone repair was attributed to a decrease in macrophage-produced low-density lipoprotein receptor-related protein 1 (Lrp1) that rejuvenate fracture repair." (PMID 39060500, 2024).
bone osteosarcoma (1 paper, 2020). A usually aggressive malignant bone-forming mesenchymal neoplasm arising from the bone. "To visualise delivery to the NAE, we used MG63, human bone osteosarcoma cells expressing high levels of LRP1." (PMID 33082422, 2020).
brain glioma (1 paper, 2025). A malignant glioma that involves the brain. "Similarly, the heightened expression of Low-density lipoprotein receptor-related protein-1 (LRP-1) in the BBB, brain gliomas, tumor blood vessel formation, and imitation vessels enables the peptide ligand of LRP-1 to guide polymer micelles for multi-step 'systematic' targeting of brain gliomas." (PMID 40777840, 2025).